LPAR1 (lysophosphatidic acid receptor 1)
Diseases named in the same sentence as LPAR1 in open-access papers (continued):
Sharing a sentence is not in itself a finding about the gene and the disease.
melanoma (16 papers, 2020 to 2025). A malignant, usually aggressive tumor composed of atypical, neoplastic melanocytes. "We found a statistically significant correlation between the expression of LPAR1, DR6 and IL-10 in human melanoma tissue and an association between increased expression of LPAR1 and reduced effectiveness of ICI therapy." (PMID 39187677, 2025). "In addition to our finding that PCa patients in the high LPAR5 expression group had worse survival, other LPAR subtypes were associated with poor survival such as LPAR1 in melanoma, LPAR2 in adrenocortical carcinoma, LPAR3 in pancreatic cancer, and LPAR4 in renal papillary carcinoma." (PMID 36806315, 2023). "LPA (10 μM) significantly increased IL-10 transcripts in A2058 and A375 melanoma cells, the effect was abolished by pharmacological inhibition of LPAR1 or knockdown of DR6." (PMID 39187677, 2025). "This analysis highlights the potential predictive value of LPAR1 expression in determining the response to anti-PD-1 therapy in melanoma patients." (PMID 39187677, 2025). "Based on 435 melanoma samples, LPAR1 expression strongly correlated with the expression of NF-κB1 (Spearman’s r = 0.23, P = 9.8 × 10−7), DR6 (Spearman’s r = 0.33, P = 1.9 × 10−12) and IL-10 (Spearman’s r = 0.21, P = 1.3 × 10−5)." (PMID 39187677, 2025). "Treatment with LPA alone resulted in a marked downregulation of HLA-DR in both A375 and A2058 melanoma cells, which was lost after pharmacological inhibition of LPAR1 by AM095 or siDR6-mediated silencing of DR6 expression." (PMID 39187677, 2025). "We also showed that the LPA-induced secretion of IL-10 in melanoma cells is mediated by LPAR1 and DR6." (PMID 39187677, 2025). "LPAR1 is present at high levels in NCSCs and certain melanoma cell lines but is either undetectable or barely expressed in melanocytes." (PMID 38426087, 2024). "Taken together, this suggests that while melanoma cells are dependent on LPAR1/3-mediated signalling for movement induction, the PDAC cells’ dependence lies only in the directionality LPA provides as a chemotactic signal." (PMID 38994966, 2024). "First, we analyzed the relative expression levels of various LPA receptors in human A375 and A2058 melanoma cells as representatives of primary and metastatic melanoma models, respectively, and found that both cell lines expressed predominantly LPAR1 and LPAR3." (PMID 39187677, 2025). "Moreover, LPAR1 is a crucial regulator of melanoma invasion, metastasis, and therapy resistance." (PMID 39187677, 2025). "We showed that a combination therapy with an LPAR1 inhibitor (Ki16425) and an ATX inhibitor (BMP22) is more effective in inhibiting melanoma metastasis than single therapy." (PMID 36080255, 2022). "In the C57BL/6-B16-F10 syngeneic murine melanoma lung metastasis model, we previously demonstrated that host LPAR1 and LPAR5 promote the seeding of metastases and that ATX produced by cancer cells enhances melanoma cell migration and invasion." (PMID 35326737, 2022). "In agreement with our previous studies demonstrating a complex consisting of MRTF-A and FLNA, we additionally found an interaction between MRTF-A and LPAR1 in HuH7 HCC cells and M2 melanoma cells expressing FLNA." (PMID 36577757, 2022). "LPAR1, LPAR2 and LPAR5 play essential roles in the invasion and metastasis of melanoma." (PMID 32284748, 2020). "We showed that a knockout (KO) mouse that lacked LPAR1 demonstrated strong resistance to melanoma metastasis, suggesting that stromal LPAR1 modulates B16F10 melanoma metastasis to the lung." (PMID 36080255, 2022).
pancreatic cancer (15 papers, 2012 to 2024). "But importantly, upregulation of LPAR1 transcription was also observed in 179 pancreatic cancer patient samples, suggesting it is a common alteration in PDAC." (PMID 38395755, 2024). "In particular, we previously showed that LPAR1 is important for chemotaxis of pancreatic cancer cells." (PMID 38712822, 2024). "The actin nucleation-promoting protein N-WASP controls clathrin-mediated endocytosis and endosomal recycling of LPAR1, thereby driving tumor invasion and pancreatic cancer metastasis." (PMID 36577757, 2022). "Another LPAR1/3 antagonist, Ki16198, effectively suppressed pancreatic cancer invasion and metastasis partially through inhibiting MMP production." (PMID 34209775, 2021). "Several other studies have also shown that LPAR1 can promote the metastasis and invasion of pancreatic cancer cells, while LPAR2 has the opposite effect 81,82." (PMID 32284748, 2020). "Taken together, these data show that the N-WASP-SNX18 complex is essential for LPAR1 recycling and chemotaxis in pancreatic cancer cells." (PMID 31668663, 2019). "Thus, pancreatic cancer cells depend on LPAR1 signaling to activate a contractile response to LPA, likely crucial for coordinating motility and invasion." (PMID 31668663, 2019). "Thus, KPC cells rapidly consume LPA, creating a self-generated gradient, and both N-WASP and LPAR1 are crucial for chemotaxis of KPC pancreatic cancer cells toward serum LPA." (PMID 31668663, 2019). "Furthermore, LPAR1_2 CRISPR KPC cells formed fewer and less invasive metastatic nodules on the peritoneum and diaphragm, confirming the LPA-LPAR1 axis as a major mediator of pancreatic cancer cell invasion and dissemination in vivo." (PMID 31668663, 2019). "Similarly, increased cancer cell invasiveness mediated by LPAR1 was found in pancreatic cancer." (PMID 34209775, 2021). "Lysophosphatidic acid receptor 1 (LPAR1) not only regulates the development of intratumoral heterogeneity but also is crucial for chemotaxis and dissemination of pancreatic cancer cells." (PMID 37070074, 2023). "The contributing genes to this pathway, e.g. CCKBR, CHRM5, EDNRA, LPAR1, SSTR2/3, and SCTR, have diverse functions in regulating the endocrine and exocrine functions of the pancreas, which are highly relevant to pancreatic cancer." (PMID 23056513, 2012). "This insight suggests a potential involvement of LPAR1 in the metastatic behavior of PDAC cells, which aligns with the previous understanding of LPAR1’s influence on pancreatic tumor progression and highlights its potential as a clinical and biological marker of PDAC." (PMID 38395755, 2024). "These genes were overlapped with 9,170 DEGs in PAAD, which were obtained by comparing the mRNA expression profile between pancreatic cancer in TCGA and the normal pancreas in GTEx; six specific genes were found, including VWF, GNG11, FGF7, TNXB, IL3RA, and LPAR1." (PMID 37070074, 2023).
hepatocellular carcinoma (14 papers, 2014 to 2024). A malignant tumor that arises from hepatocytes. "This agrees with the literature data, as the structure–activity relationship of the LPAR1 in transfected rat hepatoma model cells shows the following rank order: 18:2 > 18:3 > 20:4 > 18:1 > 16:0 > 18:0." (PMID 38999980, 2024). "The LPAR1/LPAR3 expression is increased in hepatoma cell line SKHep1, and the LPA-LPAR3 signaling may play an essential role in tumor invasiveness/expansion." (PMID 30705088, 2019). "LPAR1, 3, and 6 mRNA and protein expression is high in the human hepatoma cell line HuH7." (PMID 29734668, 2018). "There is strong evidence that LPAR1 is expressed in the nucleus of different cell types, such as the pheochromocytoma of the rat adrenal medulla (PC12), human bronchial epithelial cells (HBEC), rat liver cells and rat hepatoma cells (HTC4)." (PMID 37681929, 2023). "In this study we report the microenvironment in human hepatocellular carcinoma (HCC) and non-tumor liver (NTL) is characterized by a subset of cells expressing LPAR1 and LPAR3, a profile shared by the human hepatic tumor-derived SKHep1 cell line." (PMID 26701886, 2016).
Obesity (13 papers, 2014 to 2025). Accumulation of substantial excess body fat. "A possible LPAR through which LPA mediates this effect is LPAR1 since the Lpar1-knock out KO is also resistant to diet-induced obesity as is the Enpp2-KO." (PMID 31652837, 2019).
Anxiety (10 papers, 2011 to 2024). Intense feelings of nervousness, tension, or panic often arise in response to interpersonal stresses. "Surprisingly, the observed anxiety-like phenotype found in LPAR1-deficient mice and the current results were opposite to the observed anxiolytic phenotype in LPAR5-deficient mice." (PMID 32325720, 2020). "The importance of Lpar1 in brain development has been demonstrated in reports of Lpar1-null mutant mice that exhibit defective neurogenesis in the developing cortex and adult hippocampus, along with anxiety-like behavior and spatial memory deficits." (PMID 33317583, 2020).
depression (10 papers, 2017 to 2026). "These also indicates that LPAR1 may be implicated in the mechanism of COVID-19-related depression." (PMID 40918512, 2025). "Notably, LPAR1 has emerged as a novel therapeutic target for depression and a specific new target of antidepressant interventions." (PMID 40918512, 2025). "Lpar1/Edg2 expression is downregulated in the temporal cortices of subjects with major depressive disorder compared with those of control participants and in the peripheral blood lymphocytes of schizophrenia patients compared with those of control participants." (PMID 34385905, 2021).
glioblastoma (9 papers, 2015 to 2023). The most malignant astrocytic tumor (WHO grade IV). "The authors showed that LPAR1 antagonists inhibit microglial-induced glioblastoma cell proliferation and migration." (PMID 34440828, 2021). "LPA stimulates PKCα–progesterone receptor (PR) interaction inducing receptor phosphorylation, and LPAR1-mediated upregulation of VEGF expression contributing toward glioblastoma progression." (PMID 34440828, 2021).
neuroblastoma (8 papers, 2013 to 2022). Neuroblastoma (NB) is the most common solid, extracranial childhood tumor. "Using multiple databases and analysis methods, LPAR1 was screened out through our comprehensive bioinformatics analysis and found to be positively associated with survival of neuroblastoma patients." (PMID 35884407, 2022). "It has been reported that mutated Lpar1 increases cell motility and invasion of rat neuroblastoma cells." (PMID 34385905, 2021). "However, one major finding in one of the reports was frequent activation of the RHO signaling pathway by mutations to inhibit neuritogenesis in neuroblastoma, and LPAR1 is a membrane receptor in this pathway." (PMID 24147068, 2013). "In a rat neuroblastoma cell line or mouse fibroblast cell line, overexpression of LPAR1 also markedly decreased intrinsic cell motility and invasion." (PMID 35884407, 2022). "For instance, neuroblastoma cells engineered to express a constitutively active mutant of LPA receptor 1 (LPAR1) showed an increased VEGF expression and ability to promote ECs migration respect to the normal counterpart." (PMID 29240722, 2017). "We sequenced the coding region of LPAR1 for additional 23 neuroblastoma tumors from patients aged greater than 6-year old including 14 from metastatic high-risk patients using Sanger sequencing method." (PMID 24147068, 2013). "Nevertheless, because LPAR1 is involved in the RHO pathway and the genes in this pathway have been found to be frequently mutated in neuroblastoma, we performed further biological characterization of this somatically acquired mutation." (PMID 24147068, 2013). "LPA-LPAR1 axis showed migration-inhibitory effects on neuroblastoma cells, suggesting that LPAR1 may be a potential target for future treatment of neuroblastoma." (PMID 35884407, 2022). "Mutated Lpar1 stimulates the expression and activity of MMP-2 in rat neuroblastoma cells." (PMID 34385905, 2021). "In addition, recent sequencing analyses on neuroblastoma also did not identify any mutation in LPAR1, suggesting the mutation in this gene is rare in neuroblastoma." (PMID 24147068, 2013). "LPAR1 was proved to be reduced in neuroblastoma cells compared with non-mailgant cells." (PMID 35884407, 2022).
Arthritis (7 papers, 2014 to 2023). Inflammation of a joint. "Inspection of the neighborhood on the BN suggests that PDGFRA regulate LPAR1 which may contribute to development of arthritis via cellular infiltration." (PMID 32565911, 2020). "Indeed, mice with global deletion of Lpar1 revealed a strong resistance to bone destruction in an arthritis model induced by type II collagen injection and showed decreased infiltration of macrophages and T helper cell differentiation into Th17, but not Th1 or Th2." (PMID 35408784, 2022).
breast tumors (7 papers, 2012 to 2022). "Herein we showed by analyzing publicly available expression data from 1488 human primary breast tumors that the gene encoding the transcription factor ZEB1 was the most correlated with LPAR1 encoding LPA1." (PMID 26098771, 2015). "In order to identify the genes correlated with LPAR1, we screened nine publicly available breast tumor databases (GSE2109; GSE5460; GSE1456; GSE2034; GSE12276; GSE3494; GSE2603; GSE7390; GSE16391) comprising of a total of 1488 patient samples." (PMID 26098771, 2015). "Overexpression of Lpar1 driven by the MMTV promoter in the mammary gland of transgenic mice induces the formation of spontaneous breast tumors within the first year." (PMID 24828490, 2014). "Finally, high LPAR1 expression in basal breast tumors predicted worse lung-metastasis-free survival." (PMID 26098771, 2015). "As LPA mediated up regulation of both ZEB1 and miR-21 through a common LPA1/PI3K axis, and because the strong correlation between ZEB1 and LPAR1, we examined the correlation between LPAR1, ZEB1 and miR-21 in human primary breast tumors." (PMID 26098771, 2015). "Interestingly, transgenic mouse models that expressed either human ATX, LPAR1, LPAR2 or LPAR3 displayed spontaneous development of breast tumors, while in human BC MDA-B0-2 cells, overexpression of ATX or LPAR1 resulted in invasion, bone metastasis and destruction." (PMID 36358855, 2022). "We found that the correlation between LPAR1 and ZEB1 was stronger in the basal subtype (R Spearma n = 0.59) of human primary breast tumors than the non-basal subtype (R Spearma n = 0.40)." (PMID 26098771, 2015).
colorectal cancer (7 papers, 2016 to 2025). A primary or metastatic malignant neoplasm that affects the colon or rectum. "Pertaining to the role of LPAR1 in cancer, Lpar1 mutations have been detected in liver tumors in rats, LPAR1 has been suggested as a colorectal cancer risk locus, and the ATX-LPAR1 axis has been implicated in lung carcinogenesis." (PMID 40141453, 2025). "To examine the stability of circLPAR1, we treated colorectal cancer cells with actinomycin D (an inhibitor of transcription) and observed that circLPAR1 was more stable than linear LPAR1 transcripts." (PMID 35164758, 2022). "High-throughput RNA sequencing of colorectal cancers matched with corresponding control tissue showed the downregulation of circLPAR1, a circRNA generated from circularization of exons 3 and 4 of the lysophosphatidic acid receptor 1 (LPAR1) transcript." (PMID 36831450, 2023). "Notably, hsa_circ_0087960 (derived from LPAR1, hereafter termed circLPAR1) was the only circRNA to be validated in cell lines with significantly downregulated expression in colorectal cancer cells (HCT116 and DLD1) compared with normal FHC cells." (PMID 35164758, 2022). "A model for the early-stage screening of colorectal cancer was created using seven consensus biomarkers (namely ESM1, DHRS7C, OTOP3, AADACL2, LPHN3, GABRD, and LPAR1), and yielded >98% balanced accuracy on external validation." (PMID 39484215, 2024).
liver fibrosis (7 papers, 2019 to 2022). "In line with this discovery, LPAR1 antagonism significantly reduces liver fibrosis in a murine NASH model induced by choline-deficient high-fat diet (CDHFD) in vivo, and suppresses human HSC contractility and activation in vitro, highlighting a potential strategy to target-activated HSCs." (PMID 39872749, 2022). "To further assess whether LPAR1 antagonism inhibits liver fibrosis in vivo, we used a 12-week choline-deficient high-fat diet (CDHFD) rodent model of NASH." (PMID 31722201, 2019). "LPAR1 antagonism markedly reduced liver fibrosis as measured by digital morphometry of picrosirius red and αSMA and hydroxyproline assay." (PMID 31722201, 2019). "Moreover, SML protected against liver fibrosis in a dose-dependent manner as indicated by down-regulation of LPAR1, LPAR3, CTGF, TGF-β1/Smad3, and α-SMA expressions and a decrease in pSmad3 level, as well as an up-regulation of Smad7 expression." (PMID 35648193, 2022). "To assess whether LPAR1 expression increases during the evolution of human NASH-induced liver fibrosis, we performed bulk RNA-seq of human liver samples from a cohort of biopsy-confirmed NASH patients with a range of fibrosis stages (F1–F4)." (PMID 31722201, 2019). "Finally, we identify LPAR1 as a therapeutic target on collagen-producing CaHSCs, demonstrating that blockade of LPAR1 inhibits liver fibrosis in a rodent NASH model." (PMID 31722201, 2019). "So, LPAR1/LPAR3 down-regulation could provide therapeutic benefits against hepatic fibrosis." (PMID 35648193, 2022). "LPAR1 is a particularly exciting target for the treatment of HCC, as 80% of HCCs develop in the context of liver fibrosis." (PMID 36577757, 2022). "Notably, these activated HSCs expressed high levels of lysophosphatidic acid receptor 1 (LPAR1), a G protein–coupled receptor that binds to lipid-signalling molecule LPA, and pharmacological inhibition significantly inhibited liver fibrosis." (PMID 32562113, 2020). "Having identified CaHSC as the predominant pathogenic collagen-producing cell during CCl4-induced centrilobular murine liver fibrosis, we identified that Lpar1 was expressed in CaHSC but not PaHSC following acute and chronic CCl4-induced liver injury." (PMID 31722201, 2019).
lung carcinoma (7 papers, 2020 to 2025). "For example, LPAR1 shows high expression in lung cancer tissues, making it a potential target for novel lung cancer treatment strategies." (PMID 40362442, 2025). "LPAR1 stimulates cell growth in an ADAM12-mediated manner in A549 lung cancer cells." (PMID 34440828, 2021). "LPAR1 and LPAR2 receptors are responsible for increased motility in A549-R10 lung cancer cells." (PMID 34440828, 2021).